SMAD6 (SMAD family member 6)
Description:
Acts as an inhibitory regulator of signaling mediated by the TGF-beta superfamily, with strong selectivity toward BMP-dependent pathways. Suppresses IL1R-TLR signaling through its direct interaction with PEL1, preventing NF-kappa-B activation, nuclear translocation and NF-kappa-B-mediated expression of pro-inflammatory genes. Blocks the BMP-SMAD1 signaling pathway by competing with SMAD4 for receptor-activated SMAD1-binding. Associates with regulatory elements in target promoter regions. Functions as an adapter protein that recruits ubiquitin ligases, including SMURF1 and, in some contexts, SMURF2, promoting proteasomal degradation of signaling components and transcription factors such as RUNX2, TBX6, BMPR1A and MYD88.
Synonyms: MADH6; HsT17432; AOVD2; MADH7
Tractability: PROTAC: UniProt records ubiquitination sites on it; ubiquitination databases record sites on it.
Gene: Protein-coding gene on chromosome 15 (66,702,236 to 66,782,849, forward strand). Ensembl gene ENSG00000137834.
Subcellular location: Nucleus; Cytoplasm
Subcellular location (Human Protein Atlas): Nuclear bodies; Nucleoplasm; Basal body; Cytosol; Golgi apparatus; Primary cilium
Pathways (Reactome):
Gene expression (Transcription): RUNX2 regulates bone development
Signal Transduction: Signaling by BMP
Gene Ontology:
Molecular function: chromatin binding; co-SMAD binding; I-SMAD binding; identical protein binding; protein binding; protein sequestering activity; R-SMAD binding; transcription cis-regulatory region binding; transcription regulator inhibitor activity; type I activin receptor binding; type I transforming growth factor beta receptor binding; ubiquitin protein ligase binding; ubiquitin-like ligase-substrate adaptor activity; activin receptor binding
Biological process: aortic valve morphogenesis; BMP signaling pathway; cell-substrate adhesion; fat cell differentiation; immune response; negative regulation of activin receptor signaling pathway; negative regulation of apoptotic process; negative regulation of BMP signaling pathway; negative regulation of cell population proliferation; negative regulation of MyD88-dependent toll-like receptor signaling pathway; negative regulation of osteoblast differentiation; negative regulation of SMAD protein signal transduction; negative regulation of transforming growth factor beta receptor signaling pathway; proteasome-mediated ubiquitin-dependent protein catabolic process; response to laminar fluid shear stress; response to lipopolysaccharide; zygotic specification of dorsal/ventral axis; anatomical structure morphogenesis; cell differentiation; mitral valve morphogenesis; negative regulation of ossification; outflow tract septum morphogenesis; pulmonary valve morphogenesis; regulation of transcription by RNA polymerase II; SMAD protein signal transduction; and 7 more
Cellular component: cytoplasm; nuclear body; nucleoplasm; nucleus; protein-containing complex; chromatin; cytosol; heteromeric SMAD protein complex; transcription regulator complex
Genetic constraint (gnomAD): Loss-of-function variants: 97 observed, 34.79 expected, observed/expected ratio (o/e) 2.79. The synonymous counts are far from expectation, so gnomAD's model fits this gene poorly and the ratio says little. Missense variants: 1,102 observed, 595.14 expected, observed/expected ratio (o/e) 1.85, 90% interval 1.76 to 1.94. Synonymous variants: 444 observed, 273.45 expected, observed/expected ratio (o/e) 1.62, 90% interval 1.5 to 1.76.
Homologues: Orthologues: chimpanzee SMAD6 (99% identical), macaque SMAD6 (99% identical), pig SMAD6 (97% identical), dog SMAD6 (95% identical), rat Smad6 (93% identical), mouse Smad6 (93% identical), guinea pig SMAD6 (91% identical), zebrafish smad6b (62% identical), zebrafish smad6a (52% identical), tropical clawed frog smad6 (50% identical), Caenorhabditis elegans daf-14 (15% identical). Paralogues in human: SMAD7 (43% identical), SMAD9 (26% identical), SMAD4 (26% identical), SMAD1 (24% identical), SMAD5 (24% identical), SMAD2 (24% identical), SMAD3 (23% identical).
Diseases named in the same sentence as SMAD6 in open-access papers:
SMAD6 is named in the same sentence as 124 diseases in open-access papers, as found by Europe PMC text mining. Sharing a sentence is not in itself a finding about the gene and the disease. The quoted sentences say what the papers report.
craniosynostosis (23 papers, 2016 to 2025). Craniosynostosis is defined as the premature fusion of one or more cranial sutures leading to secondary distortion of skull shape resulting in skull deformities with a variable presentation. "In contrast, loss-of-function variants in SMAD6 are primarily associated with craniosynostosis, where skeletal malformations dominate, and neurological effects are limited." (PMID 41300846, 2025). "In this patient we were able to identify for the first time all three so far known SMAD6 associated phenotypes in a single individual including radioulnar synostosis, congenital heart defects and craniosynostosis in addition to PAH as a novel SMAD6 phenotype." (PMID 40133303, 2025). "Our data support the current observation that there is no increased prevalence of thoracic aortic aneurysmal disease in SMAD6-variant positive families with craniosynostosis or vice versa." (PMID 38290823, 2024). "Until now, rare heterozygous loss-of-function variants in SMAD6 were demonstrated to increase the risk of disparate clinical disorders including cardiovascular disease, craniosynostosis and radioulnar synostosis." (PMID 38290823, 2024). "Our data expand the spectrum of variants and phenotypic spectrum associated with homozygous variants of SMAD6 to include craniosynostosis." (PMID 38290823, 2024). "Recent reports focusing on patients with non-syndromic craniosynostosis showed that single nucleotide polymorphisms (SNPs) were found in a Smad6 exon and a putative enhancer region of BMP2, and frameshift mutations in Smad6 were found." (PMID 37275223, 2023). "Consistently, our patient had a heterozygous truncating SMAD6 variant also reported in a patient with isolated craniosynostosis, in which the proband’s parent transmitting the SMAD6 variant was apparently unaffected, as in the present family." (PMID 34208845, 2021). "Heterozygous mutations in SMAD6 have been reported to underlie craniosynostosis, speech delay, global developmental delay, fine motor impairment and aortic valve abnormalities with variable penetrance (see ‘Discussion’ section)." (PMID 32005695, 2020). "Rare damaging variants in SMAD6 alone impart very large effects on disease risk with low penetrance, with inheritance at BMP2 explaining nearly all of the variation in occurrence of craniosynostosis seen among SMAD6 mutation carriers." (PMID 27606499, 2016). "In sum, inheritance at rs1884302 explains nearly all of the variation in phenotype among subjects with SMAD6 mutations and demonstrates two locus transmission of craniosynostosis." (PMID 27606499, 2016). "This search revealed that rare mutations that disable one copy of a gene called SMAD6 in combination with a common DNA variant near another gene called BMP2 account for about 7% of infants with midline forms of craniosynostosis." (PMID 27606499, 2016). "Rare damaging SMAD6 mutations were found in nearly 25% of kindreds with recurrent midline craniosynostosis, and 37.5% of patients with combined sagittal and metopic craniosynostosis in our cohort." (PMID 27606499, 2016). "Fourteen individuals had both a SMAD6 mutation and the rs1884302 risk allele; 100% of these had craniosynostosis." (PMID 27606499, 2016). "Confining analysis just to subjects with SMAD6 mutation, there was dramatically increased occurrence of craniosynostosis among those with the rs1884302 risk allele compared to those without (p=4.8 × 10–6 by Fisher’s exact test)." (PMID 27606499, 2016). "SMAD6 mutations were significantly more frequent in kindreds with any metopic craniosynostosis (10 of 78, 12.8%) compared to those with isolated sagittal craniosynostosis (3 of 113, 2.7%; p=8.1 × 10–3 by Fisher’s exact test, odds ratio 5.3)." (PMID 27606499, 2016).
craniosynostosis (continued). "Inspired by large studies in other genetic disciplines in which such occurrences are well documented, focusing on non-syndromic midline craniosynostosis caused by rare SMAD6 variants, for example, we should organize large registries of detailed, well-curated phenotypes." (PMID 41608500, 2025). "Additionally, craniosynostosis and radioulnar synostosis have been described in patients with pathogenic SMAD6 variants." (PMID 40133303, 2025). "A SMAD6 variant was associated with premature craniosynostosis and hip dislocation, while TCF4 mutations (Pitt-Hopkins syndrome) produced characteristic facial anomalies, including coarse facial features, a protruding lower face, full cheeks, and cupid’s bow upper lip, in two distinct patients." (PMID 41300846, 2025). "Here, we present the first two patients with craniosynostosis harbouring homozygous SMAD6 variants." (PMID 38290823, 2024). "To conclude, our report expands the spectrum of phenotypes identified in individuals with homozygous SMAD6 variants to include craniosynostosis, and emphasises the importance of complementing genetic studies with functional assessment for variant interpretation." (PMID 38290823, 2024). "Additionally, haploinsufficiency of the BMP-specific inhibitory Smad SMAD6 is predicted to be a modifier of the penetrance of craniosynostosis, with mutations in SMAD6 increasing the risk of developing craniosynostosis." (PMID 38385025, 2024). "In addition, pathogenic variants in SMAD6, the most common monogenic cause of metopic synostosis, are correlated with suboptimal neurodevelopment in non‐syndromic craniosynostosis." (PMID 38417842, 2024). "We determined the occurrence of SMAD6 variants in all types of craniosynostosis,evaluated the impact of different missense variants on SMAD6 function, andtested independently whether rs1884302 genotype significantly modifies thephenotype." (PMID 32499606, 2020). "SMAD6 is associated with not only BAV but also susceptibility of craniosynostosis." (PMID 30848080, 2019). "Interestingly, these SMAD6 mutation-only cases thus far have all had isolated metopic craniosynostosis." (PMID 27606499, 2016). "Interestingly, transmitted SMAD6 mutations were significantly enriched in kindreds with familial craniosynostosis, accounting for 4 of 17 kindreds with more than one affected subject (p=0.02, Fisher’s exact test; odds ratio 5.6)." (PMID 27606499, 2016). "Collectively, the significant burden of both de novo and rare transmitted mutations, along with significant association results in case-control analysis provide extremely strong evidence that rare damaging SMAD6 alleles impart large effects on risk of non-syndromic midline craniosynostosis." (PMID 27606499, 2016). "R81 methylation may be significant in the context of craniofacial development and cranial suture closure because compromised Smad6 function has been associated with the occurrence of craniosynostosis, a congenital condition characterized by premature fusion of bones that form the cranial vault." (PMID 33667543, 2021). "Epistatic interactions have been described for cystic fibrosis (CFTR) and DCNT4 or craniosynostosis (SMAD6) and BMP2 amongst others." (PMID 37477760, 2023). "Over the past 10 years, genetic variants in SMAD6 were demonstrated to impinge on the risk of human genetic disorders such as cardiovascular diseases, including congenital heart defects (CHD), craniosynostosis (CRS) and radioulnar synostosis (RUS)." (PMID 36414630, 2022). "A previous study identified rare SMAD6 and common BMP2 alleles involved with craniosynostosis in humans." (PMID 34539446, 2021). "This was typically because one parent had only the SMAD6 mutation while the other had only the common BMP2 variant; the transmission of both to their offspring resulted in craniosynostosis." (PMID 27606499, 2016).
craniosynostosis (continued). "Lastly, we compared the joint segregation of rare damaging SMAD6 and common BMP2 risk alleles to the segregation of craniosynostosis in a parametric two locus linkage model in these kindreds." (PMID 27606499, 2016). "We advocate for testing SMAD6 variants in PAH patients, particularly those with complex congenital heart defects or unclear cardiovascular abnormalities, as well as PAH patients with craniosynostosis or radial synostosis." (PMID 40133303, 2025). "Craniosynostosis was present in both patients described here, unlike those previously reported with biallelic SMAD6 variants." (PMID 38290823, 2024). "In this report, we describe two patients, both harbouring a homozygous damaging SMAD6 variant, and both affected with metopic craniosynostosis and radioulnar synostosis, but without typical cardiac and outflow tract abnormalities." (PMID 38290823, 2024). "Exome sequencing of parent–offspring trios identified SMAD6 mutations with incomplete (<60%) penetrance causing non-syndromic midline (sagittal and metopic) craniosynostosis." (PMID 35451466, 2022). "Pathogenic SMAD6 variantssubstantially increase the risk of both nonsyndromic and syndromic presentationsof craniosynostosis, especially metopic synostosis." (PMID 32499606, 2020). "In contrast, 16 subjects had a SMAD6 mutation but no rs1884302 risk allele; only 3 of these individuals (19%) had craniosynostosis." (PMID 27606499, 2016). "However, when an individual has both the SMAD6 mutation and the BMP2 risk allele (which on its own leads to the disorder in just 0.08% of cases), craniosynostosis occurs 100% of the time." (PMID 27687826, 2016). "The combination of a rare damaging SMAD6 mutation plus a common BMP2 risk allele conferred 100% risk of craniosynostosis in our cohort, while those with a SMAD6 mutation but no BMP2 risk allele were at markedly lower risk." (PMID 27606499, 2016). "More recently, mutations in Zic family member 1 (ZIC1); SMAD family member 6 (SMAD6); HECT, UBA and WWE domain-containing 1, E3 ubiquitin protein ligase (HUWE1); and smoothened, frizzled class receptor (SMO) have been identified as causal in the development of craniosynostosis." (PMID 35451466, 2022). "Available data, however, support a model in which loss-of-function SMAD6 variants are likely to result in variable phenotypes depending on concomitant genetic or environmental factors, as proved by the recurrence of the same variants in patients affected with either BAV/TAA or craniosynostosis." (PMID 34208845, 2021). "SMAD6 mutations with and without BMP2 risk alleles account for ~7% of probands in this cohort of non-syndromic midline craniosynostosis." (PMID 27606499, 2016). "Many of the variants in BMP signaling components (e.g., SMAD6, BMP2, BMP7) increase the risk of craniosynostosis rather than causing craniosynostosis directly, suggesting that interactions between pathways (namely, BMP and FGF) may contribute to the etiology of this disorder." (PMID 38385025, 2024).
lung carcinoma (9 papers, 2012 to 2023). "SMAD6 supports lung cancer cell growth as well as breast cancer cell invasion, resulting in reduced patient survival." (PMID 34848693, 2021). "SMAD6 was reported to support the growth and survival of lung cancer." (PMID 36067196, 2022). "SMAD6 correlated with poor patient survival among non-small cell lung cancer, and its knockdown inhibited cell proliferation and increased apoptosis in the lung cancer cell line." (PMID 33193701, 2020). "Moreover, SMAD6 contributes to lung cancer progression by limiting TGF-β-mediated growth inhibition of cell lines, which was proven by knockdown of SMAD6 that resulted in increased apoptosis in lung cancer cell line." (PMID 22943793, 2012). "Furthermore, Smad6 and Smad7 correlate with poor prognosis in lung cancer and gastric carcinomas." (PMID 23049692, 2012). "Studies related to lung cancer have found that the expressions of SMAD6, SMAD7, and SMAD9 in SMADs are downregulated in lung cancer and significantly correlated with the prognosis of patients." (PMID 36969909, 2023).
thoracic aortic aneurysm (8 papers, 2017 to 2025). An aneurysm formed in the wall of the proximal portion of the descending aorta proceeding from the arch of the aorta. "In an additional patient, genetic analysis revealed a vous variant in the SMAD6 gene, which is reported to be causally related to valvular and vascular defects, including bicuspid aortic valve and thoracic aortic aneurysm." (PMID 41010011, 2025). "In a large BAV/TAA cohort, SMAD6 variants were specifically enriched among patients with concurrent thoracic aortic aneurysms, while NOTCH1 and ACTA2 mutations were also documented in familial or heritable forms of aortic valve disease and aortic wall pathology." (PMID 41002609, 2025). "However, only a few of the SMAD6 variants presented as BAV were accompanied by thoracic aortic aneurysm, while most of the variants presented variable clinical phenotypes." (PMID 34295254, 2021). "The transcriptional regulator encoded by SMAD6 gene (15q22.31, OMIM 602931) has also been confirmed to be related to BAV and associated thoracic aortic aneurysm." (PMID 34071740, 2021). "The SMAD6 gene variation is associated with thoracic aortic aneurysm in patients with non-syndrome BAV." (PMID 34295254, 2021).